BRAF (B-Raf proto-oncogene, serine/threonine kinase)
Diseases named in the same sentence as BRAF in open-access papers (continued):
Sharing a sentence is not in itself a finding about the gene and the disease.
melanoma (continued). "Several oncogenes have been identified in melanoma as BRAF, NRAS, c-Kit, and GNA11 GNAQ, each capable of activating MAPK pathway, although NRAS and c-Kit also activate PI3 kinase pathway, including being more commonly BRAF activated oncogene." (PMID 23476798, 2013). "Given the high concordance of BRAF and NRAF mutations in melanoma and their associated nevi we consider this possibility highly unlikely." (PMID 23861977, 2013). "The ability of dinaciclib to induce apoptosis in the melanoma cell line panel was unrelated to either CDK2 expression levels or BRAF/NRAS mutational status, suggesting that this drug had broad-spectrum anti-melanoma activity." (PMID 23527225, 2013). "Results of phase II and III clinical trials with the first BRAF mutant selective inhibitor validated in clinic, vemurafenib/PLX4032, have revealed an impressive short-term disease stabilization in melanoma patients with BRAFV600E mutation." (PMID 24161908, 2013). "To examine the combinatorial effect of HDAC and mutant BRAF inhibitors on melanoma cells in vivo, we transplanted subcutaneously MM200 and Sk-Mel-28 cells, which were resistant to PLX4720 or SAHA alone in vitro,36 into nu/nu mice." (PMID 23744355, 2013). "Preclinical studies with MEK inhibitors reported that BRAF mutant melanoma cells growing both in vitro and in vivo as xenografts were more responsive to MEK inhibition than cell lines with wild type BRAF status." (PMID 23658559, 2013). "In conclusion, we propose a new paradigm in therapeutic strategy aimed at increasing mitochondrial oxidative stress to eradicate melanoma resistant to BRAF inhibitors." (PMID 24161908, 2013). "Of the melanoma patients treated with Sunitinib, 11% had mutations in KIT [other patients presented with mutations in BRAF (23%), NRAS (14%), or GNAQ (0%)]." (PMID 23515890, 2013). "These mutant BRAF-selective inhibitors can be particularly useful in combination with immunotherapies for melanoma." (PMID 23755373, 2013). "We have observed that BRAF inhibitor-resistant melanomas develop an addiction to mitochondrial oxidative metabolism characterized by high levels of basal mitochondrial respiration and ROS production." (PMID 24161908, 2013). "Namely, in the prior report, PRMT5 was shown to associate with CRAF in PC12 and Cos7 cells, and modulate ERK signaling in BRAF wild type melanoma cells activated with human growth hormone." (PMID 24098663, 2013). "In melanoma, the most commonly mutated component of the MAPK pathway is the BRAF gene; among others, the most prevalent BRAF mutation (nearly, 90% of cases) is represented by a substitution of valine with glutamic acid at position 600 (V600E)." (PMID 23317446, 2013). "Oncogenic BRAF transforms immortalized melanocytes and it stimulates proliferation of melanoma cells." (PMID 24416617, 2013). "Prevalence and distribution of pathogenetic mutations in BRAF and NRAS genes were evaluated in multiple melanoma lesions from patients with different geographical origin within the same Italian population." (PMID 23987572, 2013). "At the RNA level, there was good positive correlation between levels of CDK2 and the transcription factor MITF in both BRAF-V600E and NRAS mutated melanoma cell lines." (PMID 23527225, 2013). "When profiling the kinase substrates in BRAF wild-type melanoma cell line (MelJD), we observed that kinase inhibition upon in-vitro vemurafenib treatment occurred to a similar degree as in the vemurafenib-sensitive cell line (MM200) harboring BRAF(V600E)." (PMID 24023633, 2013). "Newer treatments were established in the last years that elicit unprecedented response rates in late stage melanoma, for example, up to 80% in the case of BRAF inhibitors." (PMID 23634303, 2013). "We also show that, despite the use of several combinations of in-house tests, the false result rate for BRAF testing in melanoma was low." (PMID 24119386, 2013).
melanoma (continued). "Rare tumors are addicted to single activated oncogenes, recently exemplified by bcr-abl in CML, ALK in 4% of NSCLC, and BRAF in certain melanomas." (PMID 23577104, 2013). "A thyroid sample and a CRC sample each had one false positive in NRAS, whereas one melanoma sample had two false negatives in BRAF and a false positive in KRAS." (PMID 23991070, 2013). "Here, we review the evolution of melanoma treatment from single-agent chemotherapy to combination therapy, the emergence of immunotherapy in melanoma and the development of targeted therapies, such as the use of the BRAF inhibitor as a treatment agent." (PMID 23420786, 2013). "The inability of targeted BRAF inhibitors to produce long-lasting improvement in the clinical outcome of melanoma highlights a need to identify additional approaches to inhibit melanoma growth." (PMID 24358901, 2013). "Targeting oncogenic pathways has led to recent exciting advances in multiple cancers, including vemurafenib in BRAF mutant melanoma, erlotinib in EGFR mutant non-small cell lung cancer, and crizotinib in lung cancer with the EMLA4-ALK translocation." (PMID 23593290, 2013). "We observed that Ras-mutated cells, either melanomas or colon carcinomas, were killed by the doses of IPA3, which affected the morphology, but were hardly the viability of BRAF-mutated cells of similar origin." (PMID 22869096, 2012). "Currently, mutational profiles are applied for selection of targeted therapeutics for e.g. BRAF inhibitors in malignant melanoma and BRAF and EGFR targeting in lung- and colorectal cancers." (PMID 23300780, 2012). "NCT01037127 is a phase II clinical trial to examine the effectiveness of GSK112012 in melanoma patients containing a mutant BRAF gene." (PMID 23085539, 2012). "In CHL1 melanoma cell line with wild-type BRAF, MEK inhibitor suppressed ERK phosphorylation and induced pAKT." (PMID 22880048, 2012). "Melanoma cell lines with known sensitivity to BRAF inhibitors displayed marked suppression of the MAPK pathway in this system, while most BRAF inhibitor-resistant cell lines showed intact MAPK pathway activity despite exposure to a BRAF inhibitor (PLX-4720)." (PMID 23285177, 2012). "Rap1 activation via downregulation of RapGAP1 was suggested to support ERK activation (even in BRAF mutant melanomas) and migration of melanoma cells in vitro." (PMID 22535842, 2012). "Our findings in cultured melanoma cells suggest that the presence of activated PI3K or BRAF does induce consistent, albeit unexpected changes in global cellular signalling." (PMID 22475322, 2012). "For instance, the cooperation between BRAF mutation and PTEN loss in melanoma progression has been identified." (PMID 23056577, 2012). "Many primary melanomas appear to be comprised of at least 2 malignant subclones that differ with respect to their BRAF genotype (mutant or wild-type)." (PMID 22235286, 2012). "An additional study observed that the mutant BRAF V600E gene was amplified in 4 out of 20 melanoma patients which were resistant to B-Raf inhibitors." (PMID 23085539, 2012). "There is also a Phase II trial testing the efficacy of the AZD6244 MEK inhibitor and MK-2206 AKT inhibitor in patients with relapsed BRAF V600E melanoma (NCT01510444, ClinicalTrials.gov)." (PMID 23039341, 2012). "Sorafenib was tested in melanoma as a BRAF inhibitor in combination with chemotherapy in both first and second line phase 3 trials, but failed to provide an improvement in outcome compared to chemotherapy alone." (PMID 22433222, 2012). "Vemurafenib, also known as PLX4032, RG7204, or RO5185436, is potent and specific inhibitor of the V600E BRAF activity, recently approved for the treatment of advanced melanoma." (PMID 22216021, 2012).
melanoma (continued). "Similar to acquired resistance seen with other targeted therapies, including EGFR mutant lung cancers and v-raf murine sarcoma viral oncogene homolog B1 (BRAF) mutant melanomas, there are case reports demonstrating acquired resistance to crizotinib." (PMID 25031955, 2012). "PLX-4720 is effective against melanomas, as well as colorectal cancer (CRC) and other cancers, with the BRAF V600E mutation." (PMID 23085539, 2012). "The relevance of these approaches has recently been demonstrated by the demonstration of a marked early reduction in 18F-FDG uptake in BRAF mutant melanoma using the novel BRAF inhibitor, vemurafenib." (PMID 22790877, 2012). "Pharmacodynamic information regarding the ex vivo effect of BRAF inhibitors on the MAPK pathway in live human melanoma samples can be reproducibly determined using a novel automated platform." (PMID 23285177, 2012). "Despite the first promising results in cell culture and animal studies, sorafenib was found to be unsuccessful in melanoma patients treatment even among those harboring mutant BRAF." (PMID 23056577, 2012). "Melanoma (40–60%) and papillary thyroid carcinoma (PTC; 40%–80%) are the tumors with the highest incidence of BRAF mutations." (PMID 22558339, 2012). "A problem with treatment of melanoma patients with mutant BRAF is the emergence of inhibitor-resistance which occurs frequently and relatively rapidly after treatment with the Raf inhibitors (2-18 months)." (PMID 23085539, 2012). "It has been examined in clinical trials primarily with patients having BRAF mutations (CRC, melanoma, PTC and NSCLC)." (PMID 23085539, 2012). "This miRNA is located in a DNA region frequently amplified in melanoma cells, flanked by c-Met and BRAF oncogenes and was found upregulated in melanoma cell lines." (PMID 21860617, 2012). "MITF is sometimes amplified in certain subsets of melanoma cells and cooperates with mutant BRAF to regulate melanoma proliferation." (PMID 23006971, 2012). "We found that a substantial proportion of individual tumor specimens contained a mixture of BRAF mutant and wild-type melanoma cells." (PMID 22235286, 2012). "BRAF exon 15 was amplified from single CTC from 9 out of 11 melanoma patients and BRAF exon 15 sequences were obtained from 14 individual CTC." (PMID 22281663, 2012). "Melanomas harbouring mutant BRAF and wildtype RAS are intimately dependent on ERK signalling for their growth and survival and selective RAF inhibition in these lines efficiently blocks ERK activation and growth." (PMID 23039341, 2012). "Raf inhibitors such as vemurafenib, dabrafenib, and GDC-0879 are promising for the treatment of melanoma, CRC, thyroid and other solid cancers and leukemias/lymphomas/myelomas which have mutations at BRAF V600E." (PMID 23085539, 2012). "As has proven to be the case in V600E BRAF mutant melanoma there is a compelling rationale for targeting this population of patients with BRAF inhibitors." (PMID 25562798, 2012). "For example, melanoma cells demonstrate marked differences in response to MEK1/2 inhibition, with BRAF and RAS mutational status thought to predict sensitivity and resistance, respectively." (PMID 23039341, 2012). "The V600E BRAF inhibitor, vemurafenib, is now an approved agent for the treatment of advanced melanoma." (PMID 22216021, 2012). "Recent studies in melanoma have indicated that some components of the PI3K pathway (PTEN, MTOR, IRS4, PIK3R1, PIK3R4, PIK3R5 and NFKB1) are co-mutated in 17% of BRAF V600E mutant and 9% of NRAS mutant melanomas." (PMID 23006971, 2012). "To date, studies of BRAF resistance in melanoma have identified several mechanisms that bypass the pharmacologic block of mutant BRAF." (PMID 22235286, 2012). "Recent clinical studies have shown that most BRAF mutant positive melanoma patients treated with mutant-BRAFV600 specific inhibitors, like vemurafenib, initially have a dramatic clinical response." (PMID 22912864, 2012).
melanoma (continued). "Mutation of BRAF or RAS can contribute to the pathogenesis of many cancers, including, melanoma and colo-rectal cancer." (PMID 23455493, 2012). "By contrast, chemical mediated inhibition of mutant BRAF (PLX4032) or MEK (PD0325901) triggered less killing of melanoma cells, although they did inhibit proliferation." (PMID 22277029, 2012). "Dabrafenib is in ongoing Phase II clinical trials (NCT01153763) as a single agent in patients with BRAF mutant melanoma." (PMID 23085539, 2012). "Our preliminary studies with melanoma cell lines confirmed that functional signaling profiles from this ex vivo system accurately predicted BRAF inhibitor sensitivity in virtually all cell lines, based on their genotype, known biology, and IC50 values." (PMID 23285177, 2012). "The BRAF sequences identified in the CTC were inconsistent with those identified in autologous melanoma tumours in three patients and the KIT sequences were inconsistent in three patients." (PMID 22281663, 2012). "Recently, the BRAF oncogene has been identified as an important upstream kinase for driving MAPK signaling in melanoma." (PMID 22912864, 2012). "As a foundation for subsequent studies in murine xenografts and humans, a series of 13 BRAF V600E mutant melanoma cell lines was tested for sensitivity to BRAF inhibition by determining the IC50 values of each cell line to PLX-4720." (PMID 23285177, 2012). "Vemurafenib (PLX4720/RG7204), a novel BRAF inhibitor with high specificity to BRAFV600E has potent cytotoxicity against melanoma cells in vitro and in vivo and clinically has improved survival of melanoma patients." (PMID 23372575, 2012). "Bosenberg’s group elegantly demonstrated that in a genetically modified mutated BRAF transgenic mouse model, the deletion of a functional PTEN can drive the development of malignant melanoma." (PMID 23372575, 2012). "Models VARI-LTM-044 colorectal cancer and VARI-LTM-034 pancreatic cancer both had a single KRAS mutation; melanoma models VARI-LTM-086 and VARI-LTM-027 had BRAF and NRAS mutations, respectively." (PMID 22709571, 2012). "AKT activation in BRAF mutant cutaneous melanomas mediates resistance to MEK inhibition with selumetinib." (PMID 22808163, 2012). "In recent years, BRAF and KIT have become established therapeutic targets in melanoma patients showing activating mutations in these oncogenes." (PMID 22281663, 2012). "There are innumerable reviews of the role of various biomarkers such as KRAS in colorectal cancer or BRAF in melanoma." (PMID 25562407, 2012). "Members of the Ras/RAF/MEK/ERK pathway, in particular KRAS and BRAF, are frequently deregulated in several cancers including melanoma, colorectal (CRC), non-small cell lung cancer (NSCLC) and pancreatic." (PMID 22343622, 2012). "BRAF genotyping from single melanoma cells showed heterogeneity within metastatic lesions and primary tumours." (PMID 22281663, 2012). "The combination of trametinib and the PI3K/mTOR dual inhibitor GSK2126458 also enhanced cell growth inhibition in these B-Raf inhibitor-resistant BRAF mutant melanoma lines." (PMID 23085539, 2012). "NRAS is the most commonly mutated Ras family member in melanoma, KRAS is predominantly mutated in colon cancer, while BRAF mutations are found in either malignancy." (PMID 22869096, 2012). "In conclusion, we used highly sensitive BRAF mutation detection methods and observed substantial evidence for heterogeneity of the BRAFV600E mutation within individual melanoma tumor specimens, and among multiple specimens from individual patients." (PMID 22235286, 2012). "So far, BRAF inhibitor PLX4032 is one of the only few promising treatments for malignant melanoma approved by the US Food and Drug Administration." (PMID 23056577, 2012). "When CHL1 melanoma cells (wild-type BRAF) were treated with BRAF inhibitor vemurafenib, it induced the paradoxical elevation of ERK phosphorylation as expected in wild-type BRAF cells, but triggered no change of pAKT." (PMID 22880048, 2012).
melanoma (continued). "Due to the prevalence of BRAF mutations in melanoma, the MAPK pathway has emerged as a prime target of molecularly targeted agents for this disease, including an approved inhibitor of BRAF (vemurafenib) and additional emerging inhibitors of BRAF and MEK." (PMID 23285177, 2012). "Vemurafenib, a FDA-approved BRAF inhibitor for the treatment of BRAF-mutant melanoma, has only had a modest response rate in CRC." (PMID 22792460, 2012). "In the present study, BRAF heterogeneity was also detected within metastatic melanomas through the analysis of DNA isolated from dozens of tumour cells." (PMID 22281663, 2012). "In this proof-of-concept study we have focused on the ex vivo modulation of the MAPK pathway in melanoma cells by a BRAF inhibitor; however, the analysis of other relevant pathways is also possible." (PMID 23285177, 2012). "In three cases in which primary melanomas showed BRAFV600E mutation, CTC shared a similar BRAF genotype with the primary tumours (Nos." (PMID 22281663, 2012). "A series of 13 melanoma cell lines was briefly exposed to a BRAF inhibitor (PLX-4720) on a platform employing automated fluidics for sample processing." (PMID 23285177, 2012). "Although BRAF and NRAS mutations are mutually exclusive in the majority of melanomas, dual pathway signalling is also frequently seen in melanoma through functional loss (deletion, silencing and/or mutation) of the tumour suppressor gene PTEN." (PMID 21139585, 2011). "Comparison of genes amplified in our samples with published gene lists from two large melanoma studies while revealing very little overlap did identify BRAF, MDM2, and NRAS, genes known to be important in melanoma." (PMID 21494657, 2011). "In four of the five primary melanomas, although the majority of the cells were BRAF-wild type, we observed a substantial number of melanoma cells harbouring the V600E mutation." (PMID 21224857, 2011). "The advent of highly specific inhibitors for oncogenic BRAF with robust activity in BRAFV600E mutant melanoma and the clinical development of specific inhibitors of PI3K, AKT and mTOR, provide the tools to translate these concepts into the clinic." (PMID 22194965, 2011). "In another report of 68 patients with melanoma, 30 of whom had mutant BRAF, an increase in the incidence of liver metastases was noticed in the mutBRAF group." (PMID 22039425, 2011). "Cell elongation and prominent actin stress fibers, therefore, correlate with viable melanoma cells in the presence of BRAF inhibitors." (PMID 21917148, 2011). "Based on these observations, clinical trials are underway to block MEK in patients whose BRAFV600E mutant melanoma had a response but then progressed on BRAF inhibitors like vemurafenib or dabrafenib." (PMID 22194965, 2011). "The true value of these agents must await phase II and phase III trials in patients with BRAF mutant melanoma." (PMID 22175026, 2011). "With BRAF being established as the first point of vulnerability in melanoma, it is hoped that a molecular understanding of the limits of BRAF inhibition will lead to further clinical benefit." (PMID 22175026, 2011). "Inhibitors of MEK, the downstream mediator of RAF activation, and the only known substrate of BRAF have shown promise in preclinical studies in melanoma and have begun to be investigated in the clinic with some encouraging results." (PMID 22175026, 2011). "The initial use of BRAF targeted therapeutics in clinical trials has demonstrated encouraging responses in melanoma patients, although a rise in drug-resistant cells capable of advancing malignant disease has been described." (PMID 21917148, 2011). "The combination of the BRAF inhibitor vemurafenib (formerly PLX4032) and metformin were tested against a panel of human melanoma cell lines with defined BRAF and NRAS mutations for effects on viability, cell cycle and apoptosis." (PMID 21609436, 2011).